REN (renin)
Diseases named in the same sentence as REN in open-access papers (continued):
Sharing a sentence is not in itself a finding about the gene and the disease.
Hyponatremia (continued). "The interlinking of increased secretion of arginine vasopressin (AVP)-enhanced activity of the sympathetic nervous system and the renin-angiotensin system plays a paramount factor in the development of hyponatremia." (PMID 30408132, 2018). "Chronic hyponatremia has been associated with cognitive dysfunction and dementia because of the hyponatremia- inducing activation of renin- angiotensin- system, increases in inflammatory cytokines and oxidative stress, and decreases in ATP production." (PMID 29940017, 2018). "On the third day of life, he manifested hypotension with high urine output, hyponatremia, hyperkalemia, hypernatriuria, high plasma adrenocorticotropic hormone level, and high plasma renin activity, suggesting acute adrenal insufficiency." (PMID 29506479, 2018). "Hyponatremia is directly proportional to the degree of vasodilation, which leads to activation of the renin-angiotensin-aldosterone system (RAAS), a major mediator in hepatic fibrogenesis." (PMID 28409147, 2017). "The fall of the peripheral blood pressure and hyponatraemia, both observed in our study, would normally activate the renin-angiotensin system to re-adjust the physiological blood pressure." (PMID 28572613, 2017). "Lab work revealed hyponatremia, an elevated peripheral renin activity, aldosterone and ADH levels, and a normal serum creatinine." (PMID 26000267, 2015). "Lab work revealed significant hyponatremia, elevated peripheral renin activity, and increase in aldosterone and ADH levels." (PMID 26000267, 2015). "Hyponatremia is rare in patients with central adrenocortical insufficiency because the sodium balance is mainly regulated by the renin-angiotensin system." (PMID 24597969, 2014). "It was shown that PAH patients have elevated levels of norepinephrine, renin, aldosterone, elevated plasma volume and hyponatremia in advanced disease." (PMID 24251953, 2013). "Group II, SIADH, had increased FEurate, hyponatremia, and decreased baseline plasma renin and aldosterone levels." (PMID 24358843, 2013). "Both hyponatremia and a decreased ratio could be explained by impairment of the renin–angiotensin–aldosterone axis and ADH secretion in B. caballi-infected horses." (PMID 40711303, 2025). "Therefore, the water retention and hyponatremia occurred by active renin-angiotensin-aldosterone system and arginine-vasopressin system." (PMID 36830256, 2023). "Normalizing sodium levels can not only prevent critical adverse events from hyponatremia but may be beneficial by decreasing renin–angiotensin–aldosterone system (RAAS) activation, improving diuretic efficacy and improving infant growth." (PMID 35053719, 2022). "Therefore, in this patient, low level of the renin-angiotensin-aldosterone system, hypopituitarism, and the inappropriate production of vasopressin by the pNET jointly resulted in hyponatremia." (PMID 34622867, 2021). "The potential mechanism of action is unclear, but BBs indirectly inhibit angiotensin II via inhibition of renin secretion; this, in turn, may lead to hyponatremia (see the following discussion about ARBs)." (PMID 32285124, 2020). "This hypovolemic state may have contributed to hyponatremia development, due to vasopressin secretion, and stimulus of renin-angiotensin-aldosterone system, as suggested by others." (PMID 28231825, 2017). "This volume depletion may lead to serum osmolality increase and vasopressin release, as well as renin-angiotensin-aldosterone system activation, leading to hyponatremia." (PMID 28231825, 2017). "However, any final recommendation regarding the exact dosage of albumin will require prospective, randomized control trials incorporating serum renin as an outcome parameter along with renal impairment and hyponatremia." (PMID 26150850, 2015).
Hyponatremia (continued). "A rapid rise in arterial pressure can cause glomerular hyperfiltration and pressure natriuresis in the non-stenotic kidney, causing volume depletion and hyponatremia, which may result in further renin release from the ischemic kidney." (PMID 40493279, 2025). "In contrast to the well-defined hypervolemic dilutional hyponatremia which can occur as a result of peripheral vasodilatation, kidney hypoperfusion, and increased activation of the renin-angiotensin-aldosterone system, desalination could also be the result of daily taps." (PMID 37410459, 2023). "Furthermore, cardiac dysfunction may increase brain natriuretic peptide secretion, which can act on the kidney, inhibit the renin and aldosterone release, increase urinary sodium excretion, and possibly lead to hyponatremia." (PMID 37884881, 2023). "Loss of intravascular volume (in hypovolemic hyponatremia) and loss of effective intravascular volume (in hypervolemic hyponatremia) can activate the neurohumoral axis, resulting in increased secretion of AVP, renin, angiotensin II, aldosterone, and catecholamines." (PMID 34558033, 2022). "The prognostic significance of hyponatremia in chronic left heart failure (LHF) reflects the strong correlation between serum sodium and plasma neurohormone concentrations, such as norepinephrine, renin, and angiotensin II, all of which are linked to poor outcome in advanced LHF." (PMID 33535666, 2021). "Compensatory mechanisms counteracting the low cardiac output include stimulation of the renin-angiotensin-aldosterone system, sympathetic nervous system and release of vasopressin, which contribute to an increase in blood volume and, therefore, to hyponatremia and pleural effusion." (PMID 32059573, 2020). "In HF, hyponatremia is a product of several simultaneous pathophysiological mechanisms, including arterial underfilling, activation of the sympathetic nervous system and renin-angiotensin-aldosterone system, enhanced arginine vasopressin secretion, renal impairment and diuretic therapy." (PMID 32746925, 2020). "The hyponatremia was associated with a 7% reduction in blood volume as determined by the gold standard radioisotope dilution method, using 51 chromium labeled red blood cells and RISA, increased baseline plasma renin, aldosterone, and ADH and low normal atrial natriuretic peptide." (PMID 26237607, 2014). "During hospitalization, the patient developed symptomatic hyponatremia three times and each laboratory analysis revealed improperly high levels of antidiuretic hormone without signs of extracellular fluid volume depletion as well as remarkably high plasma renin activities and angiotensin levels." (PMID 22738362, 2012). "Loss of intravascular volume (in hypovolemic hyponatremia) and effective intravascular volume (in hypervolemic hyponatremia) activated the neurohumoral axis, leading to increased secretion of AVP, renin, angiotensin II, aldosterone, and catecholamines." (PMID 36157210, 2022). "In the first week of life, they showed hyponatremia and primary adrenal insufficiency with a slight 17OHP elevation and increased DHEAS and renin levels." (PMID 36553457, 2022). "With regard to the endocrine dysfunctions associated with DMRs for the aldosterone pathway, a few cases of unexplained severe hyponatremia were reported in patients with PWS, although the levels of aldosterone and renin were normal." (PMID 34389046, 2021). "Dehydration following treatment according to the acute respiratory distress syndrome (ARDS) protocol together with the virus disturbing endocrine functions, like the Renin-angiotensin-aldosterone system (RAAS), would be expected to shift the electrolyte pattern from hyponatremia to hypernatremia." (PMID 34156969, 2021). "One patient (P4) also had transient hyponatremia and high renin level but he did not need MC replacement." (PMID 32938577, 2021).
Hyponatremia (continued). "Furthermore, hyponatraemia in the black African population may indicate a greater degree of sodium imbalance compared with other ethnic groups as the black population physiologically have increased sodium retention with lower plasma renin and aldosterone levels." (PMID 32832115, 2020). "Furthermore, hyponatremia was prevented via the strong blockade of RAS using a therapeutic combination of the angiotensin II receptor blocker, Candesartan, and the direct renin inhibitor, Aliskiren." (PMID 22738362, 2012). "In contrast, in the case of hyponatremia, activation of the renin–angiotensin–aldosterone system along with inhibition of vasopressin induces upregulation of salt retention in the kidney without water retention, resulting in normalization of hyponatremia." (PMID 33809466, 2021). "The non-osmotic arginine vasopressin (AVP), the renin-angiotensin-aldosterone axis, and the sympathetic nervous system activate vascular resistance and enhance sodium and water renal retention, leading to hyponatremia in hospitalized patients with HF." (PMID 34680582, 2021). "Previous studies have focused on patients with chronic heart failure, in which hyponatremia was shown to be related to neurohormonal activation, such as the non-osmotic release of vasopressin, activation of the renin-angiotensin system, and increased catecholamine production." (PMID 26053619, 2015). "However, hyponatremia has not been demonstrated to occur as a result of combined therapy with candesartan cilexetil, an angiotensin II receptor blocker, and aliskiren fumarate, a direct renin inhibitor." (PMID 22738362, 2012). "Each episode of hyponatremia was accompanied with improperly high levels of ADH, extremely high plasma renin activities and high angiotensin levels without signs of extracellular fluid volume depletion." (PMID 22738362, 2012).
acute kidney injury (115 papers, 2008 to 2026). Sudden and sustained deterioration of the kidney function characterized by decreased glomerular filtration rate, increased serum creatinine or oliguria. "The risk of acute renal failure increases by 4.5-fold in men taking fluoroquinolone antibiotics in combination with renin–angiotensin system blockers." (PMID 36986665, 2023). "A close relationship between sepsis-associated acute kidney injury and renin-angiotensin system was noticed." (PMID 33746749, 2021). "Portal hypertension leads to vasodilatation of splanchnic vessels, decrease in systemic vascular resistance, and activation of the renin-angiotensin-aldosterone causing vasoconstriction of renal arteries, decreased renal perfusion, and renal failure." (PMID 33381474, 2020). "The adverse effects are due to the anti-renin properties and range from hyperkalemia to functional acute kidney injury (AKI), especially in patients with underlying chronic kidney disease, bilateral renal artery stenosis, or solitary kidney." (PMID 33194923, 2020). "This recommendation is based on adult literature and expert consensus, given the risk of precipitating acute kidney injury ACE inhibitors should be used cautiously in paediatric patients with volume depletion because their elevated renin levels can lead to hypotension." (PMID 41007039, 2025). "Elevated renin levels could also be used to identify high-risk patients for acute kidney injury (AKI) and the need for renal replacement therapy." (PMID 40880376, 2025). "The increased renin activity with hypoaldosteronism observed in our study aligns with previous findings in septic shock, where this increase was associated with increased renal failure." (PMID 40126750, 2025). "However, further evidence is required to fully explain the heightened risk of developing acute kidney injuries when renin inhibitors are combined with ACEi/ARB medications." (PMID 38332893, 2024). "It is likely that the REN pathogenic variant predisposed him to acute kidney injury." (PMID 39722771, 2024). "A sharp rise in renin levels and angiotensin II are linked to the onset of malignant hypertension and renal failure is discovered, and the mechanism is yet unknown." (PMID 38660003, 2024). "The risk of acute kidney injury induced by renin–angiotensin system blockers may increase after renal failure (with dehydration or other drug administration)." (PMID 36986665, 2023). "The renin-AngII system can cause microvascular damage and accelerate the progression of acute tubular necrosis and cortical necrosis, potentially leading to irreversible renal failure." (PMID 36052061, 2022). "Such risk stratification would provide information for better targeting of interventions such as improved blood pressure control, use of renin angiotensin aldosterone system inhibitors, cardiovascular risk reduction and acute kidney injury (AKI) avoidance." (PMID 25700182, 2015). "Hyperaldosteronism can be due to adrenal hyperplasia or neoplasia, or it can attributed to the activation of the renin–angiotensin system because of cardiovascular or renal failure." (PMID 40282004, 2025). "The parathyroid hormone level of patients with severe acute renal failure in the control groups was (88.5 ± 6.7) pg/L, and the renin level of patients with severe acute renal failure in the control groups." (PMID 37547338, 2023). "After the steroid and renin-angiotensin system inhibitor use, purpura and acute kidney injury recovered within a month." (PMID 36522629, 2022). "The activation of renin-angiotensin system and an elevated angiotensin II (Ang II) level are involved in various forms of acute kidney injury." (PMID 33746749, 2021). "The nephrotoxic potential of dual or triple combinations of NSAIDs with renin–angiotensin system inhibitors and/or diuretics yields a high incidence of acute kidney injury." (PMID 35295466, 2021).
acute kidney injury (continued). "Renal failure results in disturbed renal metabolic activities with reduced renin, erythropoietin, and vitamin D production, which adversely affects the immune system." (PMID 32635646, 2020). "HU and gout are mainly associated with ADTKD—uromodulin (UMOD) and ADTKD—renin (REN) genetic forms, sometimes starting in the teenage years but usually preceding development of renal failure." (PMID 32106421, 2020). "In a review, it was found that the prevalence of inappropriate medications in general population patients with renal failure was between 1% and 37%, with antidiabetics, renin‒angiotensin axis-blocking drugs, and uricosuric drugs involved most frequently." (PMID 31238559, 2019). "To date, new insights for the treatment of AS are expected from the EARLY PRO-TECT Alport trail that is evaluating the effect of renin-angiotensin blockade on proteinuria and renal failure progression." (PMID 29946535, 2018). "The concurrent use of (a) diuretics, (b) renin–angiotensin–aldosterone system inhibitors (RAASIs), and (c) non-steroidal anti-inflammatory drugs (NSAIDs) or metamizole, known as the triple whammy (TW) combination, increases the risk of acute kidney injury (AKI)." (PMID 40423496, 2025). "Laboratory data indicated renal failure with proteinuria (creatinine 3.93 mg/dL, proteinuria 4.0 g/day), hypokalemia (potassium 2.7 mEq/L), and secondary hyperaldosteronism as a result of excessive renin activity (131.9 ng/mL/h)." (PMID 39349898, 2025). "Multiple studies have shown that critically ill patients with increased plasma renin concentration are more likely to develop organ failure, including acute kidney injury (AKI) or the composite outcome of major adverse kidney events (MAKE), and are more likely to die." (PMID 39593182, 2024). "Clinical data show that after replacement therapy and hemodialysis in patients with severe acute renal failure in the observation group, the levels of parathyroid hormone, renin, and quality of life were all improved, with an improvement rate of 9.47%, which has certain promotional value." (PMID 37547338, 2023). "Acute kidney injury (AKI) associated with “Triple Whammy” drug therapy consisting of renin-angiotensin system inhibitors, diuretics, and nonsteroidal anti-inflammatory drugs (NSAIDs) has been reported." (PMID 35139129, 2022). "The downregulation of Gla gene expression in PAT may lead to renal failure and some cardiovascular and cerebrovascular diseases through the renin-angiotensin-aldosterone system and renal parenchymal injury." (PMID 33679891, 2021). "Future studies are warranted to delineate the detailed effects of BNP inhibition in kidney cGMP levels and acute renal failure in sepsis, as well as to clarify likely interactions with the arterial and venous vasculature, sympathetic nervous system, and the renin-angiotensin-aldosterone system." (PMID 32324169, 2020). "A previous study in Spain showed that the most common ADRs leading to hospitalization were acute renal failure induced by renin-angiotensin system inhibitors, gastrointestinal bleeding related to anti-thrombotics and/or NSAIDs, and intracranial bleeding caused by vitamin K antagonists." (PMID 33303036, 2020). "The hemolysis-mediated complement activation could be an additional key element in this vicious circle, linking renin secretion, vascular damage and renal failure." (PMID 30619356, 2018). "And activation of the renin-angiotensin-aldosterone system may lead to acute tubular necrosis and acute renal failure." (PMID 22957294, 2012). "BACKGROUND: Concomitant use of renin–angiotensin system inhibitors (RASIs), diuretics, and nonsteroidal anti-inflammatory drugs (NSAIDs), commonly referred to as the “triple whammy” (TW), is known to increase the risk of acute kidney injury (AKI)." (PMID 41794774, 2026).